C5 (complement C5)
Diseases named in the same sentence as C5 in open-access papers (continued):
Sharing a sentence is not in itself a finding about the gene and the disease.
autoimmune disease (11 papers, 2010 to 2025). A disorder resulting from loss of function or tissue destruction of an organ or multiple organs, arising from humoral or cellular immune responses of the individual to their own tissue constituents. "Thus, the functional study of TRAF1/C5 with autoimmune disease may provide an insight into the pathogenesis and treatment of these diseases as well as RA." (PMID 21492465, 2011). "The C5 blockers which acts effectively against the formation of MAC therefore is currently available and widely used in practice to treat autoimmune diseases." (PMID 31752725, 2019).
atherosclerosis (10 papers, 2012 to 2025). A disease characterized by the build-up of fatty material and calcium deposition in the arterial wall resulting in partial or complete occlusion of the arterial lumen. "Studies have shown that complement inhibition using a neutralizing anti-mouse C5 antibody attenuates atherosclerosis, indicating the importance of the terminal complement pathway in disease progression." (PMID 40119227, 2025). "Meanwhile, the serum level of C5 was positive with coronary calcification in atherosclerosis patients." (PMID 37002701, 2023). "This has been supported by the fact that circulating C5 was significantly elevated in patients with subclinical atherosclerosis and was positively correlated with plaque volume and coronary calcification." (PMID 37629447, 2023). "Exercise reduces the expression of C5 in the aorta, thereby downregulating the infiltration of macrophages, further improving the progression of atherosclerosis, and thus has a protective effect on the pathogenesis of atherosclerosis." (PMID 35205118, 2022). "We showed that anti-C5 treatment was beneficial against atherosclerosis by limiting the total lesion size and severity." (PMID 36142647, 2022). "In this study, we investigated, for the first time, the effect of limiting terminal complement activation on both NASH and atherosclerosis in one model simultaneously, by treatment with an established anti-C5 blocking monoclonal antibody (BB5.1)." (PMID 36142647, 2022). "In our study, we further investigated the effect of anti-C5 treatment on the development of atherosclerosis." (PMID 36142647, 2022). "APOE was reported to attenuate unresolvable inflammation as a checkpoint by complex formation with activated C1q in the complement activation pathway and subsequently reducing C5 and the inflammatory burden in atherosclerosis and Alzheimer disease." (PMID 35379280, 2022). "Anti-C5 did, however, reduce the development of atherosclerosis, limiting the total lesion size and severity independently of an effect on plasma cholesterol but with reductions in oxidized LDL (oxLDL) and macrophage migration inhibitory factor (MIF)." (PMID 36142647, 2022). "In addition, similar to the results of our study, it has been reported that plaque generation from patients with AMI and atherosclerosis increased C5 levels." (PMID 34002800, 2021).
glaucoma (9 papers, 2013 to 2024). Increased pressure in the eyeball due to obstruction of the outflow of aqueous humor. "In summary, we have demonstrated that the downstream components of the complement cascade have a damaging role in glaucoma, and that the natural C5 deficiency protects D2 mice from severe glaucoma." (PMID 23806181, 2013). "On the other hand, C5 deficiency could protect DBA/2J mice from glaucoma since C5-sufficient DBA/2J mice develop a more severe glaucoma at an earlier age than standard DBA/2J mice." (PMID 32585848, 2020). "This implies that a functional C5 protein affects RGC loss in human glaucoma, and that inhibition of C5 may be a useful target for treatment." (PMID 23806181, 2013). "This study implicates the downstream components of the complement cascade in the pathogenesis of glaucoma and suggests inhibition of C5 as a potential therapy for glaucoma." (PMID 38396986, 2024). "Enhancement of several complement factors including C1q, C3, C5 and membrane attack complexes have been observed in glaucoma patients and in animal models of glaucoma." (PMID 39104531, 2024). "The DBA/2J mouse line, a commonly used mouse model for hereditary glaucoma, is C5 deficient, demonstrating that C5 is not required for the development of glaucoma in DBA/2J mice." (PMID 38396986, 2024). "We quantified the majority of key proteins associated with classical complement pathway, such as C1q, C1s, C1r, C4a, C4b, C3, C5, C6, C7, C8a, C8b, C8g and C9, as up-regulated in glaucoma condition for both vitreous and retinal tissues when compared to the controls." (PMID 28978942, 2017). "Similar to other complement proteins, C5 is present in multiple locations and cell types during glaucoma, including the retina and the optic nerve head, and it could contribute to glaucoma in multiple ways including modulation of IOP elevation." (PMID 23806181, 2013). "They found a significant increase in the expression of complement proteins (C1R, C2, C4A/C4B, C5, C6, C8A, C9, CFB, CFI, and VTN) in glaucoma patients as compared to the control cataract patients." (PMID 38396986, 2024). "Consequently, intravitreal C5 inhibition might be a future therapeutic approach for glaucoma." (PMID 32676862, 2020). "The presence of downstream complement proteins necessary for MAC formation (C5 through C9) has also been confirmed in the retina and AH of glaucoma patients, but their synthesis by retinal cells has not been demonstrated." (PMID 34440742, 2021). "Thus, to determine the effects of C5 in glaucoma, we developed C5-sufficient DBA/2J mice by transferring a functional C5 gene from strain C57BL/6J." (PMID 23806181, 2013). "Therefore, to determine whether a functioning C5 gene results in MAC deposition in RGC soma in glaucoma, we localized C5b-9 in retinas from D2.C5B6 eyes with early glaucoma." (PMID 23806181, 2013). "Given that most humans have a functional C5 gene, C5-sufficient D2 mice may more closely model human glaucoma, and D2.C5B6 mice are therefore an important new strain for understanding the role of the complement cascade in glaucoma." (PMID 23806181, 2013). "Supporting an involvement of the complement system in glaucoma, in IOP-independent experimental autoimmune glaucoma model (EAG) an increase of C3 positive cells and an increase of C3 mRNA level could be found 14 days after induction, while the C5 level remained unchanged." (PMID 34943212, 2021).
myocardial infarction (9 papers, 2017 to 2025). Gross necrosis of the myocardium, as a result of interruption of the blood supply to the area, as in coronary thrombosis. "This suggests that targeting earlier components of the complement cascade may offer a more effective strategy for reducing inflammatory damage associated with acute myocardial infarction compared to C5-targeted therapies like Pexelizumab." (PMID 40119227, 2025). "Pexelizumab (Alexion, MA), a monoclonal antibody against C5 is under phase 3 clinical trials for Acute myocardial infarction and CABG." (PMID 32923410, 2020). "Accordingly, on the basis of concerns with previous studies and the results of this study we reason that there is a need to reconsider the use of complement inhibition especially at the level of C5 in clinical myocardial infarction." (PMID 28258298, 2017). "Experimental and clinical studies strongly implicate the complement system as pivotal in IRI8,10,11,29 and therapeutic depletion or inhibition of complement at the level of C3 or C5 has been found to reduce myocardial infarct size in different animal models." (PMID 29170426, 2017). "Large clinical studies have explored the efficacy of C5 inhibition using pexelizumab, a monoclonal antibody blocking C5 cleavage, on the outcome of myocardial infarction treated with thrombolysis and percutaneous coronary intervention." (PMID 28258298, 2017). "We conclude that inhibition of C5 in myocardial infarction should be reconsidered." (PMID 28258298, 2017). "We hypothesized that the C5 inhibitor coversin could reduce infarct size and improve myocardial function in a clinically relevant porcine model of acute myocardial infarction." (PMID 28258298, 2017). "We hypothesized that inhibition of C5 before reperfusion will decrease infarct size and improve ventricular function in a porcine model of myocardial infarction." (PMID 28258298, 2017). "Administration of the anti-C5 antibody during percutaneous coronary intervention neither reduced myocardial infarction nor decreased mortality." (PMID 28258298, 2017). "Inhibition of complement factor 5 (C5) reduced myocardial infarction in animal studies, while no benefit was found in clinical studies." (PMID 28258298, 2017). "Pexelizumab, another monoclonal antibody targeting complement C5, initially showed promising results in early-phase II clinical trials, such as the COMMA and CABG trials, demonstrating a 30% reduction in 30-day mortality among patients with acute myocardial infarction." (PMID 40119227, 2025).
vasculitis (9 papers, 2013 to 2025). "In an MPO-ANCA transfer mouse model, C4-deficient mice develop vasculitis after injection of anti-MPO IgG, whereas C5- and factor B-deficient mice are resistant to the development of vasculitis." (PMID 37781373, 2023). "Conversely, synovial hyperplasia, leukocyte infiltration, vasculitis and fibrosis were significantly reduced in rats after a single treatment with anti-C5 DNA." (PMID 23505550, 2013). "In particular, activation of C5 is important for inducing ANCA-vasculitis in animal models." (PMID 40430184, 2025). "However, despite these developments highlighting the role of complement components within leukocytes, our data show that activation of C5 from other sources is important in anti‐MPO vasculitis." (PMID 27235854, 2016). "Finally, in view of the recently discovered importance of intracellular complement components 16, 17, 18, 19, 20, 21, we examined the relative importance of bone marrow‐derived and circulating C5 in anti‐MPO vasculitis." (PMID 27235854, 2016). "Inhibition of C5, by using a C5-inhibiting monoclonal antibody (BB5.1), prevents ANCA-vasculitis and reduces glomerular inflammation." (PMID 40430184, 2025). "The anti-human C5/C5a antibody MEDI7814 neutralizes the C5aR1 and C5aR2 receptors; a C5aR antagonist, Avacopan (CCX168), was approved in 2022 for use in ANCA vasculitis." (PMID 38458648, 2024). "The raised levels of complement factors in the supernatant and the increased C5 expression of ANCA-activated neutrophils demonstrated that S100A8/A9 and S100A12 could promote the activation of the alternative complement pathway in MPO-ANCA-positive vasculitis." (PMID 36088289, 2022).
acute kidney injury (8 papers, 2019 to 2025). Sudden and sustained deterioration of the kidney function characterized by decreased glomerular filtration rate, increased serum creatinine or oliguria. "In patients with HUS, for instance, a higher prevalence of females, severe renal failure, and treatment with an anti-C5 antibody can be noted, and in patients with C3G, it is a higher prevalence of hypocomplementemia and severe proteinuria that can be noted." (PMID 34714369, 2022). "Another study showed immunostaining for C1q, C3c, C4c,C5, C9, and factor H were found in the kidney cortex and medulla of sheep with acute kidney injury." (PMID 31338070, 2019). "Interestingly, most patients had mild or asymptomatic COVID-19 infection, whilst HUS presented with severe haemolytic anemia and acute kidney injury requiring transfusions, hemodialysis, and the C5 inhibitor eculizumab in 7 cases." (PMID 34899761, 2021).
chronic kidney disease (8 papers, 2021 to 2025). Impairment of the renal function secondary to chronic kidney damage persisting for three or more months. "With the introduction of humanized monoclonal antibodies that inhibit C5 activation, the natural history of aHUS completely changed, with a better prognosis, a quick recovery of renal function, and a significant reduction of end-stage renal disease incidence." (PMID 37833944, 2023). "No patients receiving anti-C5 antibodies have required maintenance kidney replacement therapy to date, and fewer patients have developed hypertension, proteinuria, or chronic kidney disease." (PMID 39518638, 2024). "Importantly, intrarenal complement gene expression (C1R, C1QB, C6, C9, C5, MASP2) predicts nonresponse to induction therapy, alluding to the potential pathogenic role of intrarenal complement gene expression in chronic kidney disease." (PMID 41031884, 2025). "Several authors have suggested reclassifying HUS in two entities, regardless of they are complement-mediated or not, since the use of eculizumab, an anti-C5 antibody, dramatically lowers the proportion of patients who die or suffer from end-stage renal disease within the year following diagnosis." (PMID 35160242, 2022).
glomerular disease (8 papers, 2019 to 2026). "This dysregulation of the complement system caused by a long-term C5 inhibition is typically observed in patients with glomerular disease, who develop C3-associated deposits in the kidney comparable to those developed by patients with deficiencies in CFH and CFI28,43." (PMID 34001980, 2021). "Activation of the complement immune system and its role in renal pathophysiology has been well documented, including the role of C5 in renal inflammation in mice and 3 glomerulopathy in a mouse model and in renal fibrosis (for review)." (PMID 35723372, 2022). "Recent advances in complement-targeted therapies—including inhibitors of C3, C5, factor B, and MASP-2—are entering glomerular disease trials, with early evidence of efficacy in proteinuria reduction and slowing of glomerular injury." (PMID 41792651, 2026).
hemolytic-uremic syndrome (8 papers, 2012 to 2025). Acute kidney injury associated with microangiopathic hemolytic anemia and thrombocytopenia. "ADAMTS13 activity was later found to be within normal limit, hence diagnosis of atypical hemolytic uremic syndrome was strongly considered at that time and she was immediately treated with anti-C5 humanized monoclonal antibody (eculizumab)." (PMID 28101432, 2017). "In addition, the C5 inhibitor eculizumab, which is already approved by the FDA for PNH, was also tested as treatment for several other diseases, including kidney transplants and haemolytic uraemic syndrome (HUS)." (PMID 23346185, 2012).
systemic lupus erythematosus (8 papers, 2010 to 2022). An autoimmune multi-organ disease typically associated with vasculopathy and autoantibody production. "In other connective tissue diseases such as systemic lupus erythematosus (SLE), activation of the complement system, primarily C5, is a cause of thrombotic microangiopathy." (PMID 35207487, 2022). "The success of inhibiting C5 cleavage in murine lupus has prompted a single-dose placebo-controlled phase I study to investigate the safety, pharmacodynamics, and pharmacokinetics of eculizumab in 24 SLE patients." (PMID 32789005, 2020). "It was found that monoclonal antibody against C5 effectively improved lupus nephropathy in both lupus mice and patients with lupus nephropathy presenting low levels of serum complement." (PMID 31752725, 2019). "Blockade of C5 is effective in murine systemic lupus erythematosus, and there are case reports of response to C5 inhibition using eculizumab." (PMID 30655025, 2019). "Even the TRAF1/C5 association is not unique to RA as there have been reports of association with juvenile idiopathic arthritis and systemic lupus erythematosus." (PMID 20854658, 2010).
asthma (7 papers, 2011 to 2022). "C3, C5 and their receptors have also been implicated in pathogenesis of asthma, cystic fibrosis, and idiopathic pulmonary fibrosis." (PMID 35672453, 2022). "The most significant cluster as determined by average silhouette score statistic is located inside the coding sequence of Complement component 5 gene (C5) that is already known as an asthma susceptibility gene reported in previous studies." (PMID 21359210, 2011). "In summary, this validation analysis confirmed the implication of rs25681 in the C5 gene in the inflammatory context of asthma." (PMID 35205259, 2022). "Despite the promising beneficial effect of C5 inhibition on airway inflammation and AHR in murine asthma models, clinical investigations are needed to evaluate the therapeutic potential of C5 inhibition in asthma patients." (PMID 31340811, 2019). "The role of the complement system in asthma has previously been described with the main focus on C3 and C5 complexes." (PMID 26292153, 2015). "Furthermore, blocking C5 by antibody reduces type 2 responses in a house dust mite-induced murine asthma model." (PMID 35504938, 2022). "The vast majority of the identified candidate SNPs were not previously reported, apart from C5 (Complement component 5) whose polimorphisms were already associated with asthma development." (PMID 21359210, 2011). "The involvement of C5 in many diseases could be studied in a wide range of animal models including asthma, immune complex lung disease, coronary and renal ischemia-reperfusion injury (unpublished data) and in models of autoimmune peripheral neuropathy, using the treatment with OmCI." (PMID 23696894, 2013). "Although activation of C5 has been shown to enhance vascular permeability, C5 inhibition did not modulate vascular permeability in our HDM induced asthma model." (PMID 31340811, 2019).
glomerulonephritis (7 papers, 2008 to 2025). A renal disorder characterized by damage in the glomeruli. "On the other hand, the depletion of C3 using cobra venom factor and mice deficient C5 or factor B completely inhibited the development of glomerulonephritis." (PMID 35812453, 2022). "In contrast, once disease is established, excessive activation of C3 and C5 exacerbates glomerulonephritis and inflammatory injury, whereas genetic deficiency of C3 or C5 improves survival, highlighting the dualistic nature of complement in lupus pathophysiology." (PMID 41187099, 2025). "Pretreatment with a C5-inhibiting monoclonal antibody in a mouse model of anti-myeloperoxidase IgG-induced glomerulonephritis significantly reduced glomerular crescent formation." (PMID 38590952, 2024). "Notably, a C5 monoclonal antibody attenuated disease severity in a mouse model of anti-MPO induced glomerulonephritis." (PMID 35242041, 2022). "Even in vivo models support complement as a key player in the pathogenesis of AAV: complement activation by alternative pathway, in particularly C5aR, is required for the onset of glomerulonephritis, and mouse knocked-out for C5 as well as factor B–but not C4- were protected from disease onset." (PMID 35242041, 2022).
nephritis (7 papers, 2016 to 2025). Inflammation of renal tissue. "In fact, administration of an anti-C5 antibody in the mouse model of nephritis induced with MPO-ANCA almost entirely inhibited nephritis." (PMID 29259684, 2016). "Single and combined inhibition of C5 and CD14 efficiently prevented BD-induced systemic inflammation and reduced local kidney inflammation in a mouse model." (PMID 40707525, 2025). "Using mass spectrometry, we found an increase in the level of complement components C3, C4b, C5, C9, and CFB in the urine of patients with active nephritis." (PMID 37108355, 2023). "The concentration of urinary complement proteins (C3, C4, C5 and C5a) was evaluated to see if these could distinguish patients with and without nephritis in IgAV." (PMID 36227437, 2023). "In a mouse model of nephritis induced with myeloperoxidase anti-neutrophil cytoplasmic antibody (MPO-ANCA), knocking out complement factor B and complement component C5 resulted in the absence of nephritis." (PMID 29259684, 2016). "Likewise, similar C5 and C5AR1 frequencies were observed amongst IgAV patients stratified according to IgAV severity (presence/absence of nephritis)." (PMID 40717085, 2025).